TNF (tumor necrosis factor)
Diseases named in the same sentence as TNF in open-access papers (continued):
Sharing a sentence is not in itself a finding about the gene and the disease.
tumor (continued). "Increasing evidence indicates that a chronic and consistent expression of TNFα in tumors promotes tumor development and progression." (PMID 25762639, 2015). "Tumor radiation therapy is inhibited by hypoxia through Fas or TNF-α signals, which are related to hypoxia." (PMID 25742790, 2015). "In our hands, four of the five cytokines studied showed anti-tumor efficacy and one of the cytokine candidates, TNF-α, was so potent when given in combination with T-cells that some tumors disappeared completely." (PMID 26107883, 2015). "Immunostainings revealed that TRAIL was almost undetectable, while TNFα expression was distinct to strong, in the foci of reactive infiltrates, in both tumor types harvested from hrIL-27-treated mice." (PMID 25638163, 2015). "It appears that the levels of serum TNF-α are related to cancer stage, which reflects the size of the tumour." (PMID 26508818, 2015). "Among all the combined modality groups only the adjuvant TNF-α therapy to electrochemotherapy produced significant tumour growth delay compared to control tumours and resulted in tumour cures." (PMID 25810699, 2015). "The levels of TNF-α were also higher in both groups of implant-bearing tumors than those in the tumor alone." (PMID 26158775, 2015). "CD8+ T cells from CD4-cre x IKKβfl/fl mice had dramatically reduced IFN-γ and TNF-α production in response to tumor cell re-stimulation." (PMID 25648675, 2015). "The results indicated that the CD11b-deficent tumor tissue exhibited a robust 1.36-fold decrease in TNF-α expression." (PMID 26526388, 2015). "TNF α is one of the most potent anti-tumor cytokines and has become a promising therapeutic in management of cancers." (PMID 26337231, 2015). "EMT can be triggered by different signals received from tumor microenvironments, such as TNFα, TGFβ, EGF, WNTs and Notch." (PMID 25762639, 2015). "TNF is produced both by malignant cells and the invading immune component of the tumor microenvironment." (PMID 25807548, 2015). "We assumed that TNF-α also plays an important role in the process of SCL-induced apoptosis in H22 tumor cells, via regulation of the expression of Bcl-2 and Bax." (PMID 26426041, 2015). "On the other hand, IFN-γ also strongly induces expression of IDO, which reportedly contributes to tumor-induced immunosuppression, while TNF-α can induce epithelial-mesenchymal transition (EMT), an important contributor to cancer invasion and metastasis." (PMID 26305550, 2015). "The effects were systemic, as levels of thymic stromal lymphopoietin (TSLP), tumour-necrosis factor (TNF)-α and interleukin (IL)-6 were elevated in serum of tumour-free InvEE mice and increased further in tumour-bearing animals." (PMID 25575023, 2015). "First, CRAds induce anti-tumoral immunity to kill tumor cells directly or to enhance the sensitivity of infected cells to cytokines such as TNF or IFN which in turn accelerate lysis of the infected cells." (PMID 25978371, 2015). "Upon directly recognizing cancer cells, TR-CD4 express an array of effector molecules, including IL-2, IFN-γ, TNF-α, perforin and granzyme, which play critical roles in inhibiting cancer cell growth and orchestrating anti-tumor immune responses." (PMID 26447332, 2015). "We have previously demonstrated that FL-MSCs overexpressed CCL2 in response to B-cell derived TNF and identified here IL-8 as another marker of tumor-educated MSCs." (PMID 26158216, 2015). "On the other hand, TNF-α promoted tumor cell adhesion on the ECs monolayer and exhibited tumor invasion-promoting behaviors." (PMID 26631692, 2015). "Inflammatory cells in the tumor microenvironment produce TNFα, a major stimulator of Tpl2, which can promote cell survival, invasion, and angiogenesis." (PMID 25723737, 2015). "The concentrations of the following cytokines including IL-23, IL-25, IFNγ, CD40L and TNFα in WF collected from patients with T2 tumor tended to be higher than those with T1 tumor." (PMID 26313265, 2015).
tumor (continued). "Treatment with TNF-α was shown to (i) induce NK and T cell-mediated immunity, (ii) to reduce the Treg population and (iii) to decrease tumor cell survival." (PMID 25682197, 2015). "Tanshinone-1 was also found to inhibit tumor metastasis by suppressing the tumor necrosis factor-α (TNF-α)-induced transcriptional activity of nuclear factor kappa B (NFκB)." (PMID 26202747, 2015). "First, fibroblasts-activating factors such as IL-1β and TNF-α are secreted by immune and/or tumor cells in the damaged tissue environment." (PMID 26501341, 2015). "Tumor necrosis factor-α, which is predominantly secreted by T cells and macrophages, promotes carcinogenesis by inducing cell transformation/proliferation and tumor growth." (PMID 26220864, 2015). "Thirdly, NF-κB can be induced via paracrine/autocrine signaling by TNF-α from tumor cells and chemoattracted immune cells." (PMID 26516076, 2015). "Sarcomas growing in Ptx3−/− host showed a much higher macrophage and neutrophil infiltrate, and higher levels of CCL2, CXCL2, TNFα, IL-6, IL-1β, and VEGF, suggesting an exacerbated tumor-associated inflammatory response." (PMID 26075183, 2015). "TNF-α related apoptosis inducing ligand (TRAIL) is a member of the TNF (tumor necrosis factor) superfamily that can induce cell apoptosis mainly in tumor cells." (PMID 26577955, 2015). "These activated dendritic cells induced γδT17 cells to secrete IL-8, TNF-α, and GM-CSF, thus leading to accumulation of neutrophils in the tumor." (PMID 26819959, 2015). "Both neutralizing antibodies partially attenuated the expression of PD-L1 induced by the tumour cell culture supernatants, which indicated that GM-CSF and TNF-α in the tumour microenvironment are involved in the expression of PD-L1 on neutrophils." (PMID 26581194, 2015). "Our in vitro and in vivo data show that F4/80+ cells from vaccinated mice can directly kill TC1 tumor cells by mechanisms that involve phagocytosis and TNFα." (PMID 26337837, 2015). "On the other hand, CRP is also upregulated by cytokines such as IL-6 and tumor necrosis factor, and this upregulation is considered to be a systemic reaction to tumor progression." (PMID 25602444, 2015). "In this study, Pt-NPs effectively recovered the TNF-α-induced break of the ECs monolayer and decreased the number of adhered tumor cells and the spreading area of the adhered tumor cells." (PMID 26631692, 2015). "A strong anti-CD31 staining was observed in tumours treated with either CDDP or electrochemotherapy, while anti-CD31 staining in tumours treated with TNF-α was much weaker." (PMID 25810699, 2015). "It has been reported that some cell types in the tumor microenvironment such as stromal cells can secrete growth factors like hepatocyte growth factor (HGF) or tumor necrosis factor-α (TNF-α) resulting in resistance to BRAF inhibition." (PMID 25939769, 2015). "Mechanistically, CgA inhibits tumor cell-induced formation of endothelial gaps and decreases TNFα-induced vascular leakage, reduces vascular leakage within tumors, and inhibits tumor cell transendothelial migration." (PMID 25785244, 2015). "Both TNFα and IL-6 have been shown to promote tumour invasiveness and metastasis by secretion of matrix remodelling proteins matrix metalloproteinases." (PMID 25961014, 2015). "It is possible that TNFα has differing ototoxic effects based on a given tumour’s secretome or other properties of the tumour." (PMID 26690506, 2015). "Prolonged tumour growth and increased tumour curability were observed after combined treatment with TNF-α and electrochemotherapy with intravenous CDDP." (PMID 25810699, 2015). "In this study the circulating level of IL-6 was constant from one group to another, suggesting that TNF-α is more critical than IL-6 in tumor-induced muscle wasting." (PMID 25797259, 2015). "Previous studies have reported that TNF-α significantly increased the Bax genes, but significantly decreased the Bcl-2 gene level in in human tumor cells." (PMID 26426041, 2015).
tumor (continued). "TANs in turn can then influence the tumor niche through therelease of cytokines (e.g., TNF-α, IL-1β, IL-12), chemokines (members of the CXC and CCsubfamilies), ROS, and growth factors." (PMID 26108096, 2015). "HCT116 cells stably expressing either FAT10 siRNA (FATi) or control siRNA (Ctrli) were inoculated subcutaneously into athymic nude mice and low dose of TNF-α (5 μg/kg) was administered intra-tumorally once, a week after tumor graft." (PMID 26142316, 2015). "The effect of anti-IFN-γ was more potent in the reduction of surface marker expression on tumor cells when compared to anti-TNF-α, since the addition of anti-IFN-γ significantly reduced the increase in surface marker expression." (PMID 26697005, 2015). "Taken together, the tumor-induced muscle atrophy is likely due to elevated levels of TNF-α and myostatin, which act together to activate NF-κB and FoxO1 so as to amplify the expressions of calpain (autolysis) and ubiquitin ligases (ubiquitin-proteasome)." (PMID 25797259, 2015). "Different strategies have been developed to enrich the tumor environment with TNF-α, such as delivery of the TNF-α protein directly or with microspheres, delivery of the TNF-α gene using adenoviral vectors or plasmid DNA." (PMID 25682197, 2015). "On the other hand high levels of TNF-α are known to act anti-tumoural and it seems as if the pro- or anti-tumour functions of TNF-α are dependent on the site of occurrence in tumours." (PMID 25902944, 2015). "Interleukin-6 (IL-6) and tumor necrosis factor-α (TNF-α) are important proinflammatory cytokines produced by inflammatory cells as well as tumor cells." (PMID 26674205, 2015). "Proinflammatory cytokines such as TNF-α can induce DNA damage through ROS, which leads to tumor initiation." (PMID 26528286, 2015). "The spreading area of the tumor cells adhered on the ECs monolayer in TNF-α conditioned medium was larger than that of the cells in control condition (P < 0.05, Two-Sample t-test)." (PMID 26631692, 2015). "The tumor cell survival is dependent of growth factors, like TNFα, IL1β, IL6 and VEGFα secreted by mast cells, macrophages and MDSCs." (PMID 25747113, 2015). "M1 macrophages are pro-inflammatory in function, they secrete IFN-γ, IL-12 and TNF-α, and therefore effectively suppress tumor growth while M2 like TAMs secrete TGF-β, IL-10, IL-17, IL-23, VEGF, and FGF2, promote angiogenesis and tumor progression." (PMID 26198107, 2015). "Neither heat inactivation (to denature proteins) nor benzonase treatment (to degrade nucleic acids) impacted the ability of tumor CM to promote IL-6 production or inhibit LPS-dependent induction of TNF by BMMCs." (PMID 26343581, 2015). "The TNFα protein induces the expression of adhesion molecules, facilitating the invasion of metastatic tumor cells." (PMID 26112140, 2015). "On the other hand, TNF-α also participates in bone destruction, which is a major source of tumor related pain." (PMID 26538839, 2015). "Several studies have demonstrated an association between inflammation and ovarian tumorigenesis, suggesting that TNF-α is critical in the regulation of invasion, angiogenesis, and tumor metastasis." (PMID 25624918, 2015). "The prooxidative status found here in the tumoral tissue was probably sustained by its proinflammatory nature, as shown by TNF-α and NO levels in tumor samples." (PMID 26697139, 2015). "The preponderant phenotype observed in tumor stroma is a tumor promoting phenotype characterized by the expression of molecules promoting angiogenesis (e.g., VEGF-C, IL-8), tumor growth (TNF-α) and invasiveness (MMP-7, MMP-9)." (PMID 31557983, 2015). "TNF-α, IL-1β and IL-6 play important roles in the tumor microenvironment and contribute to the promotion of inflammation associated carcinogenesis." (PMID 25763529, 2015).
tumor (continued). "Except for OSM, the expression of all anti-tumor genes including TNF-α, PRF1, GZMB, FasL, TNFSF10 and CD40LG were significantly upregulated in CIK cells compared to PBMC, which were negatively correlated with expression profiles of their potential regulators." (PMID 25826780, 2015). "VEGF-A, TNF-α and IL-1α were tested, all of which are known as key molecules that regulate angiogenesis via various mechanisms, especially in the tumor microenvironment." (PMID 26204526, 2015). "Eiger is the Drosophila ortholog of Tumour Necrosis Factor alpha (TNFα) which acts as tumour suppressor and typically drives apoptosis by activation of the intrinsic death pathway though JNK." (PMID 26462024, 2015). "Toll signaling in Drosophila is known to generate a humoral response through antimicrobial peptides and to activate hemocytes that contribute to tumour clearance by TNF signalling." (PMID 26462024, 2015). "The integrity of endothelial cells (ECs) monolayer was destroyed by tumor necrosis factor-α (TNF-α) in a hemodynamic background, which facilitated the tumor cell adhesion, this situation was recovered by the administration of platinum nanoparticles (Pt-NPs)." (PMID 26631692, 2015). "Chronic inflammation is due to the action of various inflammatory mediators, including TNF-α, IL-6 and IL-17, which suppress antitumor immunity and favor tumor progression." (PMID 25663851, 2015). "In our system, TNF-α was utilized to treat both tumor cells and ECs, which can lead to ROS production in the cells." (PMID 26631692, 2015). "CD8+ T cells can induce the cytolytic death of target tumor cells or promote tumor destruction via the secretion of effector cytokines such as IFN-γ or tumor necrosis factor (TNF)-α." (PMID 25801067, 2015). "TNF-α has been proven to be an effective anticancer agent in preclinical studies, by inducing apoptotic cell death and tumor necrosis." (PMID 26426041, 2015). "Cytokines such as, IL-6, TNF-α and IL-1β have been shown to be able to increase tumor cell pro-coagulant activity, enhancing clotting activation in cancer patients." (PMID 26192925, 2015). "Down-regulation of TNF-α production in eBL patients indicates that the anti-tumor mechanism involving TNF-α is rather reduced in patients where it is most needed." (PMID 28536409, 2015). "Inflammatory factors in the tumor microenvironment activated NF-κB; constitutive NF-κB activation further upregulates major inflammatory factors, such as TNF-α, interleukin (IL)-6, IL-1 and IL-8, which are potent activators for NF-κB." (PMID 25503960, 2015). "IL-6-deficient mice are resistant to multiple myeloma, while neutralization of TNFα switches inflammation-driven metastatic growth to inflammation-induced tumour regression." (PMID 25961014, 2015). "EBERs transcription level and TNFα expression levels were elevated in tumors compared with non-tumor specimens (P < 0.0001)." (PMID 26172457, 2015). "There were high release of TNFα from both human macrophage and mouse tumor tissues in the Sal-YB1-treated group as shown by ELISA (P < 0.05)." (PMID 26286454, 2015). "In vitro studies show that TNF-α or LTA play an important role in killing infected or tumor cells by activated macrophages and cytotoxic T cells." (PMID 26108796, 2015). "Cancer cell or stromal cell production of TNF-α is involved in the development of a range of tumors; it is partially responsible for NF-κB activation in initiated tumor cells and for the cytokine network found in human cancer." (PMID 26418748, 2015). "Tumour treatment with electrochemotherapy alone or with TNF-α resulted in significantly higher platinum concentration in the whole tumours (p<0.05)." (PMID 25810699, 2015). "The secretion of cytokines such as IL-1β and TNFα in the irradiated tumor microenvironment, can affect macrophage function and phenotype." (PMID 26348470, 2015).
tumor (continued). "High expression of TNF-α in the tumor microenvironment is a common characteristic of numerous malignant tumors, which are usually associated with poor prognoses." (PMID 25435993, 2015). "Although the process of tumor cell attachment to the endothelium during metastasis is multifactorial, the production of TNF-α-induced endothelial E-selectin in tumor cells appears to be a key step in the BCLM process." (PMID 25885919, 2015). "Our results showing high levels of TNF besides increased levels of NO and nitrotyrosine suggest a possible cross talk between nitrosative stress and inflammatory mediators in tumor tissue." (PMID 26697139, 2015). "The finding that TNF-α can stimulate ANXA2-dependent secretion of IL-6 in tumor cells suggests that ANXA2 can also modulate the tumor microenvironment." (PMID 25611381, 2015). "For example, CHX is widely used to sensitize tumor cells against TNF/TRAIL-induced apoptosis, and we have previously also used CHX to sensitize tumor cells against TRAIL-induced necroptosis." (PMID 25925126, 2015). "IL-1, IL-6, and TNF-α are secreted in the inflammatory settings of cancer and induce immune cell proliferation, survival, activation, and infiltration of the tumor to execute the antitumor immune response." (PMID 26528286, 2015). "Overall, the levels of the inflammatory markers evaluated (NAG -N-acetylglucosaminidase, TNF-α –Tumor Necrosis Factor- α) were higher in both groups of implant-bearing tumors and in serum from those animals when compared with the tumor alone levels." (PMID 26158775, 2015). "In tumor-bearing mice under chemotherapy, supplementation with fish oil and selenium prevented a rise in IL-6, TNF-α and myostatin and muscle atrophy." (PMID 25797259, 2015). "To corroborate our findings in clinical samples, we examined the association of TNFα and EBER expression in NPC tumor tissues." (PMID 26172457, 2015). "It has been well established that several cytokines, including Interleukin-10 (IL-10) and Tumor Necrosis Factor α (TNFα), have a crucial role in a coordinated manner in breast carcinogenesis." (PMID 26112140, 2015). "TNF-α is an important immune mediator in the inflammatory response and has been suggested to be an endogenous tumor promoter in human carcinogenesis." (PMID 26504356, 2015). "Bayesian networks predicted that NF-κB was decoupled from cell–cell contact after stimulation with TNFα in the tumor breast cell lines HCC1954 and AU565, and these results were confirmed by forcing cells into high and low NF by altering plating densities." (PMID 26148352, 2015). "TNFα produced by tumor cells or inflammatory cells in the tumor microenvironment can promote tumor cell survival through the induction of NFκB-dependent antiapoptotic molecules." (PMID 26648665, 2015). "Proinflammatory cytokines such as interleukin-6 (IL-6) and tumour necrosis factor alpha (TNF-α) have been suggested to play a certain role in variety of tumours." (PMID 25858079, 2015). "There is growing knowledge on the mechanisms of a SMAC mimetic-mediated tumor cell sensitization that include increased caspase activation and engagement of an autocrine cell death loop via NF-κB mediated TNF-α/TNF receptor signaling." (PMID 26383618, 2015). "Pro-inflammatory cytokines, including IFN-γ, TNF-α, and IL-2 are critical in tumor initiation, promotion, and progression." (PMID 26098776, 2015). "ROS production contributes to tumor cell apoptosis following exposure to IR and other stressors such as high glucose, angiotensin, and tumor necrosis factor α." (PMID 26439804, 2015). "The increasedsecretion of TNF-α was detected in the tumor tissues by flow cytometry,qRT-PCR and immunohistochemistry." (PMID 26098663, 2015). "Tumor-derived versican (a proteoglycan which sequesters chemokines and acts as a chemo-attractant for inflammatory cells in the tumor milieu) can stimulate resident macrophages to secrete IL-6 and TNF-α in a TLR-2 dependent manner." (PMID 26608647, 2015).